ABCB1 (ATP binding cassette subfamily B member 1)
Diseases named in the same sentence as ABCB1 in open-access papers (continued):
Sharing a sentence is not in itself a finding about the gene and the disease.
prostate carcinoma (54 papers, 2008 to 2025). A carcinoma that arises from epithelial cells of the prostate gland. "Prostate cancer cells treated with docetaxel after a period express ABCB1, which is associated with TaxR genes automatically." (PMID 39003454, 2024). "It is observed that high expression levels of ABCB1 in docetaxel-resistant prostate cancer cells are the main cause of cross-resistance to cabazitaxel." (PMID 39003454, 2024). "ABCB1, a verified mechanism underlying docetaxel resistance in prostate cancer, is induced by docetaxel and diminishes its efficacy by transporting it across the cell membrane." (PMID 28455956, 2017). "All together our findings indicate that PTOV1 confers prostate cancer cells the advantages to survive docetaxel toxicity, through upregulation of ABCB1 and genes associated to docetaxel resistance and pluripotency factors." (PMID 28938627, 2017). "The 1199G > A SNP may help predict the outcomes of paclitaxel chemotherapy in cancer patients, and the ABCB1 (1199A) allele correlates with greater resistance to anti-prostate cancer therapy than the ABCB1 (1199G) allele." (PMID 29083397, 2015). "However, exposure of the prostate cancer cell lines to 5-aza-dC and the histone deacetylases inhibitor trichostatin A indicated that downregulation of ABCB1 was mainly caused by histone modifications, whereas promoter hypermethylation seemed to play a minor role." (PMID 33066132, 2020). "Zhu and his co-workers observed that the natural product apigenin inhibits the expression levels of ABCB1 and restores the sensitivity of docetaxel-resistant prostate cancer cells in vitro." (PMID 39003454, 2024). "Low levels of ABCB1 expression was documented in prostate cancer tissue samples from chemotherapy-naïve patients, suggesting acquired resistance." (PMID 39090086, 2024). "CD44-positive prostate cancer cells were also reported to be resistant to docetaxel after a few months of treatment due to the elevation of AKT-dependent drug transporter ABCB1 and expression of class III β-tubulin." (PMID 38542115, 2024). "ABCB1, also known as P-glycoprotein, was the first ABC transporter identified and is strongly associated with MDR in several cancer types, including NSCLC, breast, colorectal, and prostate cancer." (PMID 38893104, 2024). "Prostate cancer cell lines exposed to long-term treatment with high doses of a mSWI/SNF ATPase degrader developed SMARCA4 bromodomain mutations and ABCB1 overexpression as acquired mechanisms of resistance." (PMID 38464081, 2024). "Prostate cancer cell lines exposed to long-term treatment with high doses of a mSWI/SNF ATPase degrader developed SMARCA4 bromodomain mutations and ABCB1 (ATP binding cassette subfamily B member 1) overexpression as acquired mechanisms of resistance." (PMID 38557192, 2024). "Multidrug resistance has also been reported in docetaxel therapy in prostate cancer cells with high expression of ABCB1." (PMID 38534761, 2024). "Overall, our data indicates that ITZ can revert ABCB1-mediated DTX resistance in prostate cancer cells, through inhibition of ABCB1." (PMID 35721223, 2022). "Prostatectomies from 336 chemo-naïve castration resistant prostate cancer (CRPC) patients, were used to assess the potential of ABCB1 expression as a predictive biomarker for DTX resistance in prostate cancer." (PMID 35721223, 2022). "This study investigated multiple approaches targeting ABCB1 to resensitize DTX-resistant (DTXR) prostate cancer cell lines." (PMID 36614114, 2022). "ABCB1 promoter methylation has been found to be inversely correlated with ABCB1 expression at the mRNA and/or protein level in prostate cancer and acute leukemia." (PMID 33066132, 2020). "In prostate cancer PCa, the transporter ABCB1 has been extensively studied and has proven to be important for the progression of the disease." (PMID 32587767, 2020).
prostate carcinoma (continued). "Hypermethylation of the ABCB1 promoter has been detected in more than 70% of prostate cancer tissues while it occurred rarely in normal prostate tissues." (PMID 33066132, 2020). "The functional role of ABCB1 promoter methylation in prostate cancer, however, remains to be elucidated." (PMID 33066132, 2020). "The ABCB1 downstream promoter has been found to be commonly hypermethylated in breast and prostate cancer as well as in acute leukemia." (PMID 33066132, 2020). "Apigenin inhibits ABCB1 expression and re-sensitizes docetaxel-resistant prostate cancer DU145 cells to docetaxel." (PMID 31245292, 2019). "Overexpression of ABCB1 is regarded as an important mechanism involved in the acquisition of docetaxel resistance in prostate cancer." (PMID 28455956, 2017). "Previous reports showed that androgen ablation affected the expression level of p-glycoprotein (ABCB1), Myxovirus resistanse A (MxA), and Y-box binding protein-1 (YB-1) in prostate cancer cell." (PMID 29152111, 2017). "In the prostate cancer cell line PC-3, both the ABCB1 (79%) and the ABCG2 (97%) promoter were highly methylated." (PMID 27689338, 2016). "Hypermethylation of the ABCB1 promoter has already been reported for several prostate cancer cell lines including PC-3, DU145 and ND1 cells." (PMID 27689338, 2016). "Kuguacin J, isolated from M. charantia leaves, has been reported as inhibitor of P-glycoprotein (ABCB1) activity in vitro and exerted a strong growth inhibitory effect on androgen-independent human prostate cancer (PC3) cell line in vitro." (PMID 25945113, 2015). "The prostate cancer study detected a significant correlation of ABCB1 promoter hypermethylation with worse clinicopathological features." (PMID 24380367, 2013). "In doxorubicin-resistant human uterine sarcoma (MES-SA/Dx5), apigenin reduces intracellular glutathione (GSH) levels by inhibiting ATP-binding cassette subfamily B member 1 (ABCB1), while in prostate cancer, it reverses doxorubicin resistance by down-regulating ABCB1 protein expression." (PMID 40490812, 2025). "Additionally, in the MDA-146-12 prostate cancer patient-derived xenograft model, we found an upregulation of ABCB1 after 43 d of treatment with AU-15330." (PMID 38557192, 2024). "Additionally, we characterized two independent potential resistance mechanisms to mSWI/SNF PROTAC degraders in prostate cancer models: one driven by mutations in the bromodomain of SMARCA4 and the other driven by ABCB1 elevation." (PMID 38557192, 2024). "To determine if the effect of ITZ on drug resistance was independent of androgen receptor (AR) activity, we investigated if ITZ could reverse DTX resistance in AR-negative ABCB1-overexpressing prostate cancer cell lines." (PMID 35721223, 2022). "Taken together, our data suggest that despite the importance of ABCB1 in multidrug resistance, its expression cannot be utilized as a biomarker to identify those prostate cancer patients that may be resistant to DTX prior to chemotherapy." (PMID 35721223, 2022). "Recent studies have shown that ABCB1 could potentially modulate docetaxel resistance in prostate cancer." (PMID 34094978, 2021). "Initial studies applied SHH ligand to LnCAP prostate cancer and Seg-1 oesophagus cell lines, wherein ABCB1 was upregulated and endogenous ABCB1 could be downregulated by GLI siRNA." (PMID 35582031, 2021). "In addition, the coexpression of CD147 and ABCB1 has also been reported in prostate cancer, which implies a potential relationship of these proteins in BECs." (PMID 33987940, 2021). "Five genes including ABCB1 were hypermethylated in prostate cancer cell lines." (PMID 33066132, 2020). "Collectively, our findings suggest that ABCB1 upregulation may be another mechanism of AXL-mediated docetaxel resistance in prostate cancer." (PMID 28455956, 2017).
prostate carcinoma (continued). "The upregulation of ABCB1 might be a major mechanism of taxane resistance in the early response to docetaxel in advanced tumors, and in Du145, 22Rv1 and C4-2B prostate cancer cell lines." (PMID 28938627, 2017). "Taken together, more studies may be necessary to determine the exact roles ABCB1 plays in AXL-mediated resistance to docetaxel in prostate cancer." (PMID 28455956, 2017). "In addition to cholesterol, studies have shown that elevated ABCB1 also effluxes DHT in LnCaP prostate cancer cells, which would further serve a role in anti-androgen accumulation." (PMID 23919967, 2013). "This is underlined by recent observations in prostate carcinoma cells, showing that the protein expression of ABCB1 and ABCC1 were independent of tissue oxygen levels." (PMID 22029974, 2011). "While ABCB1 siRNAs were able to restore drug sensitivity in daunorubicin-resistant gastric, hepatic, and pancreatic tumour cell lines, they showed little ability to restore drug sensitivity in paclitaxel-resistant PC-3-TxR prostate cancer cells." (PMID 18980695, 2008). "In our study, we created numerous independent AU-15330-resistant prostate cancer lines and identified two classes of resistance mechanisms: one mechanism by which mutations occur in the drug binding site of SMARCA4 and another mechanism by which ABCB1 is overexpressed." (PMID 38557192, 2024). "In a C4-2B prostate cancer cell line-derived xenograft (CDX) model described in our previous study, we detected ABCB1 overexpression at the transcript and protein levels in the tumors at endpoint (day 24), but not at day five." (PMID 38557192, 2024). "MDR development in cancer is clinically associated with the overexpression of the efflux transporter P-gp (P-gp, ABCB1) or MRP1 (MRP1, ABCC1) in numerous malignancies, including lung, breast, neuroblastoma, and prostate cancers." (PMID 36064415, 2022). "In paclitaxel-resistant prostate cancer PC3 cells, ETS1 silencing inhibited the activity of the ABCB1 promoter, which contains ETS binding sites, reduced ABCB1 protein, and reversed resistance to paclitaxel, an antimicrotubule drug." (PMID 35582031, 2021). "The ABCB1 promoter has been found to be hypermethylated in a large percentage of primary prostate cancers, whereas it was almost never methylated in benign tissues." (PMID 33066132, 2020). "The ABCB1 promoter was hypermethylated in 38.2% of samples from patients without prostate cancer recurrence and in 16.1% of patients with biochemical recurrence after radical prostatectomy." (PMID 33066132, 2020). "In most cell lines, the ABCB1 promoter was higher methylated than the ABCG2 promoter, with the exception of the two small cell lung cancer cell lines GLC-4 and DMS114, the non-small cell lung cancer cell line A549 and the prostate cancer cell line PC-3." (PMID 27689338, 2016). "Similarly, in an independent study, we demonstrated that castration-resistant prostate cancer cells also depend on BRPF1 in docetaxel and cabazitaxel resistance, highlighting BRPF1’s role as an ABCB1 regulator controlling mTOR and unfolded protein response (UPR) signaling." (PMID 40583060, 2025). "However, all 315 prostate cancer tissue samples from patients who underwent radical prostatectomy we examined were negative for ABCB1 expression, suggesting increased levels of ABCB1 expression occur as a resistance mechanism only after exposure to DTX." (PMID 35721223, 2022).
melanoma (53 papers, 1989 to 2025). A malignant, usually aggressive tumor composed of atypical, neoplastic melanocytes. "In melanoma cell lines, ABCB1 expression has been linked with migration and invasion." (PMID 24098529, 2013). "There is some, albeit limited, evidence that expression of genes encoding membrane efflux pumps (ABC transport proteins), including MRP-1 (ABCC1) and multi-drug resistant 1(MDR1)/P-gp (ABCB1), may be associated with this chemo-resistance and so with the incurable nature of malignant melanomas." (PMID 20234362, 2010). "Resistance in melanoma BMs with BRAFV600 mutations is primarily mediated by drug efflux transporters, including P-glycoprotein (P-gp; ABCB1) and breast cancer resistance protein (BCRP; ABCG2), located at the BBB and impeding penetration into BMs." (PMID 40076927, 2025). "For example, ABCB1 is overexpressed in pancreatic CSCs, ABCG2 in breast CSCs, ABCB1 and ABCB5 in melanoma, and ABCB1 in ovarian CSCs." (PMID 41321388, 2025). "Gene expression analysis based upon CCLE data, showed a number of the melanoma cell lines express ABCB1, ABCB4 and ABCG2 transcripts, however levels varied widely." (PMID 38226983, 2024). "Our results demonstrate that excess GH upregulates ABC transporters, particularly ABCC1, and ABCB1 in the melanoma-derived exosomes, which in turn, can be transferred to treatment-naïve melanoma cells making them drug resistant." (PMID 39123364, 2024). "Limonene enhances radiation-induced DNA damage and cell death in melanoma cells, and sensitizes vemurafenib-resistant melanoma cells to the drug by downregulating the expression of the drug efflux pump ABCB1." (PMID 37515699, 2023). "ABCB1+ melanoma cells exhibited higher ability to form colonies in vitro and to promote both increased tumor growth and number of metastasis in vivo, when compared to ABCB1− cells." (PMID 37047018, 2023). "According to the literature, the ABCB1/Pgp transporter is preferentially expressed in stem cell-like human melanoma cells, as is ABCB5." (PMID 38136555, 2023). "Albeit the transfection of drug-sensitive human melanoma cells with wild-type ABCB1 was significantly more efficient than the transfection with glycosylation-deficient variants, both approaches yielded drug-resistant cells." (PMID 36614114, 2022). "More recently, P-gp (Abcb1) has been also identified in human and pig RPE, and Abcb5 protein, which is highly homologous to Abcb1, was found in melanoma cells and intact melanocytes." (PMID 33804686, 2021). "Several studies have also reported the overexpression of the multiple drug resistance transporter ABCB1 (MDR1) in resistant melanoma under treatment." (PMID 33916029, 2021). "Overexpression of the ATP binding cassette (ABC) transporter, ABCB1 (also known as P-glycoprotein), which causes the efflux of DOX from cancer cells is one of the mechanisms by which melanoma cells become resistant to DOX." (PMID 34206728, 2021). "In melanoma, expression of ABCB1 was shown to denote a subpopulation of highly tumorigenic and metastatic uveal melanoma cells as compared to tumor cells without ABCB1 expression." (PMID 32587767, 2020). "To address the functional importance of high ABCB1 expression, we transduced the melanoma cell line SK-MEL-2 with either an ABCB1-expressing virus or a control virus." (PMID 30042422, 2018). "In human melanoma cells, coexistence of ABCB1, ABCG2, and ABCC2 together with stem cell markers on the cell surface was observed in a subset of cells." (PMID 28623509, 2017). "And Abcb1 was also found to function in melanoma cells, but the specific role of Abcb1 in the melanomas remains to be established." (PMID 26693729, 2015). "ABCB5 expression in tumor cells was seen to correlate with clinical melanoma progression and a subpopulation of human melanoma cells was observed to coexpress ABCB1, ABCB5, and ABCC2 in addition to stem cell markers." (PMID 26649310, 2015).
melanoma (continued). "This is of relevance for the design of next-line therapies for melanomas with acquired PLX4032 resistance since ABC transporters including ABCB1, ABCC1, and ABCG2 confer multi-drug resistance." (PMID 25300205, 2014). "ABCB1+ cells from primary cell cultures of resected melanomas have higher clonogenic capacity than the immunonegative cells." (PMID 24098529, 2013). "ABCB1 expression was detected in a subset of melanoma cells, displaying a punctuated cytoplasmic or a membranous staining pattern." (PMID 24098529, 2013). "Amongst these, ABCB1, DNMT3B, EPAS1, JARID1B and TERT have previously been designated as melanoma CSC(-associated) markers (and reviewed in 13)." (PMID 24098529, 2013). "The expression of Abcb1b/ABCB1 gene was mostly dependent on HSF1 in all three tested melanoma cell lines." (PMID 24165036, 2013). "c-Abl/Arg inhibitors have been identified as substrates of drug transporters in other cell types; however, this is the first demonstration that they inhibit ABCB1 in melanoma cells." (PMID 23383209, 2013). "Remarkably, ABCB1+ cells in the primary melanomas were predominantly found at the invasive front of the tumors, reminiscent of putative CSC in other cancer types." (PMID 24098529, 2013). "ABCB1 expression has previously been correlated with aggressive melanoma phenotypes, based on Breslow’s depth, Clark’s level and lymph-node involvement." (PMID 24098529, 2013). "No obvious differences in proportion of ABCB1-immunopositive (ABCB1+) were observed between primary melanomas and metastases." (PMID 24098529, 2013). "Of note, ABCB1 immunoreactivity was not only observed in the cell membrane of some melanoma cells but sometimes in the cytoplasm." (PMID 24098529, 2013). "In order to localize ABCB1-expressing cells in melanomas in situ, a series of 20 additional patient tumor samples (7 primary melanomas and 13 corresponding metastases), different from the 38 samples analyzed above, was examined using immunohistochemistry." (PMID 24098529, 2013). "In addition, rarely focused on in melanoma models, the multidrug transporter ABCB1 was also investigated, since it is capable of the recognition and export of the inhibitor molecule from the cells." (PMID 37508582, 2023). "In a chemoresistance melanoma cell model, viability, necroptosis with DNA damage, the absorption of the applied pharmaceuticals, and the functional activity of the ABCB1 drug transporter after administration of docetaxel or docetaxel with a selected hydrophobic statin were studied." (PMID 38136555, 2023). "Furthermore, it has been shown that melanoma, breast and ovarian cancer cells depend on ABCB1 for developing multidrug resistance (MDR)." (PMID 28677036, 2017). "Interestingly, we detected ABCB1 expression in clusters of tumor cells located at the invasive front of the primary melanomas." (PMID 24098529, 2013). "The association between ABCB1 and CD44 was further proven by a study concluding that ABCB1 might interact with CD44 through the activation of extracellular signal-regulated protein kinase 1/2 (ERK1/2) and MAPK in the M14 ADR-resistant human melanoma cell line." (PMID 33801148, 2021). "This analysis showed variable RNA expression of the three efflux transporter genes ABCB1 (P-gp), ABCB4 (MDR3) and ABCG2 (BCRP) across the melanoma cell line panel." (PMID 38226983, 2024). "The GH-treated melanoma cells released exosomes with elevated levels of ABC transporters (ABCC1 and ABCB1), N-cadherin, and MMP2, enhancing drug resistance and migration in the recipient cells." (PMID 39123364, 2024). "The expression of the ABCB1 gene was found to be primarily dependent on HSF1 in all tested doxorubicin- and paclitaxel-resistant melanoma cell lines." (PMID 37958341, 2023). "Herein, we characterize cells expressing MIC markers (CD20, CD24, CD133, Sca-1, ABCB1, ABCB5, ALDHhigh) in the B16-F10 murine melanoma cell line." (PMID 35408953, 2022).